ZNF219 (zinc finger protein 219)
Description:
Transcriptional regulator. Recognizes and binds 2 copies of the core DNA sequence motif 5'-GGGGG-3'. Binds to the HMGN1 promoter and may repress HMGN1 expression. Regulates SNCA expression in primary cortical neurons. Binds to the COL2A1 promoter and activates COL2A1 expression, as part of a complex with SOX9 (By similarity). Plays a role in chondrocyte differentiation (By similarity).
Synonyms: ZFP219
Tractability: No criterion of Open Targets' tractability assessment is met for any kind of drug.
Gene: Protein-coding gene on chromosome 14 (21,090,053 to 21,104,722, reverse strand). Ensembl gene ENSG00000165804.
Subcellular location: Nucleus
Subcellular location (Human Protein Atlas): Nucleoplasm
Gene Ontology:
Molecular function: DNA binding; DNA-binding transcription factor activity; DNA-binding transcription repressor activity, RNA polymerase II-specific; protein binding; RNA polymerase II cis-regulatory region sequence-specific DNA binding; DNA-binding transcription factor activity, RNA polymerase II-specific; histamine receptor activity
Biological process: negative regulation of DNA-templated transcription; negative regulation of transcription by RNA polymerase II; regulation of DNA-templated transcription; G protein-coupled receptor signaling pathway; limb bud formation; positive regulation of chondrocyte differentiation; positive regulation of transcription by RNA polymerase II
Cellular component: nucleoplasm; nucleus; membrane
Genetic constraint (gnomAD): Loss-of-function variants: 17 observed, 33.34 expected, observed/expected ratio (o/e) 0.51, 90% interval 0.35 to 0.76. The synonymous counts are far from expectation, so gnomAD's model fits this gene poorly and the ratio says little. Missense variants: 1,009 observed, 874.05 expected, observed/expected ratio (o/e) 1.15, 90% interval 1.1 to 1.22. Synonymous variants: 517 observed, 386.61 expected, observed/expected ratio (o/e) 1.34, 90% interval 1.24 to 1.44.
Homologues: Orthologues: chimpanzee ZNF219 (99% identical), macaque ZNF219 (98% identical), pig ZNF219 (93% identical), rat Zfp219 (89% identical), guinea pig ZNF219 (89% identical), mouse Zfp219 (89% identical), dog ZNF219 (87% identical), rabbit ZNF219 (76% identical), zebrafish znf516 (24% identical), Drosophila melanogaster salr (14% identical), Drosophila melanogaster salm (13% identical), Caenorhabditis elegans sem-4 (12% identical), and 2 more. Paralogues in human: ZNF536 (36% identical), ZNF516 (21% identical), ZNF217 (18% identical), SALL3 (16% identical), SALL1 (16% identical), SALL4 (15% identical), HIVEP3 (13% identical), HIVEP2 (13% identical), BCL11B (12% identical), SALL2 (12% identical), HIVEP1 (12% identical), BCL11A (11% identical), and 2 more.
Diseases named in the same sentence as ZNF219 in open-access papers:
ZNF219 is named in the same sentence as 15 diseases in open-access papers, as found by Europe PMC text mining. Sharing a sentence is not in itself a finding about the gene and the disease. The quoted sentences say what the papers report.
Arrhythmia (1 paper, 2022). Any cardiac rhythm other than the normal sinus rhythm. "By 8 weeks of age, while ShScramble-infected mice had normal ECGs, up to 78% of Znf219-knockdown mice had more prominent arrhythmias, with episodes of bradycardia and tachycardia, suggesting a progressive phenotype." (PMID 36076959, 2022). "Aberrant expression of skeletal-muscle sarcomere proteins in mouse hearts with knocked down Znf219 translates into arrhythmias, accompanied by an increase in PR interval." (PMID 36076959, 2022). "Supporting this view, Znf219 knockdown in the adult heart induced the ectopic expression of some skeletal-muscle sarcomeric genes, which resulted in the induction of arrhythmias similar to those observed in Chd4 cKO mice." (PMID 36076959, 2022). "When Chd4 or Znf219 are removed from the cardiomyocyte, the skeletal muscle sarcomeric program is aberrantly expressed in the cardiomyocyte and this translates to the induction of arrhythmias, cardiac fibrosis, and, eventually, to heart failure." (PMID 36076959, 2022). "Knockdown of Znf219 in the HL-1 cardiomyocytic cell line and in mouse cardiomyocytes induced the ectopic expression of mRNAs and proteins of the skeletal muscle sarcomeric program, inducing heart arrhythmias." (PMID 36076959, 2022).
autism spectrum disorder (1 paper, 2016). A spectrum of developmental disorders that includes autism, and Asperger syndrome. "Among the many genes in region are ZNF219, which encodes a transcriptional partner of Sox9 essential for chondrogenesis in mice, and CHD8, mutations in which are associated with autism spectrum disorder in conjunction with macrocephaly and distinct facial features including a broad nose." (PMID 27560520, 2016).
diabetes (1 paper, 2008). "All 7 confirmed neuronal function-related genes (DCAMKL1, GAT3, GRIN2A, KCNE2, PCGF1, PEPT2, ZNF219) revealed reproducible decreases at 3 months of STZ-induced diabetes." (PMID 18554398, 2008).
liver cancer (1 paper, 2021). An epithelial or non-epithelial malignant neoplasm that arises from the liver. "Besides previously reported dysregulated genes, the current study identified new candidate genes with a putative role in liver cancer, e.g. C1orf35, PAFAH1B3, ZNF219 and others." (PMID 33541355, 2021).
lung carcinoma (1 paper, 2017). "In the lung cancer, SIOMICS identified five shared motifs, which were similar to motifs of ZNF219, PATZ1 (MAZR), SP1, IKZF1 (Lyf-1), and the CAC-binding protein, respectively." (PMID 28684851, 2017).
Parkinson disease (1 paper, 2017). A progressive degenerative disorder of the central nervous system characterized by loss of dopamine producing neurons in the substantia nigra and the presence of Lewy bodies in the substantia nigra and locus coeruleus. "Two other transcription factors, CP2 and Zinc Finger protein 219 (ZNF219), have been implicated in the development of Alzheimer’s and Parkinson’s disease, respectively." (PMID 28499347, 2017).
tumor (2 papers, 2018 to 2021). "In particular, these genes are associated with more aggressive tumor phenotype (SAL2), migration and invasion (TOX4, PRMT5, AJUBA) development and progression (ZNF219, CEBPE)." (PMID 34944989, 2021). "The ZNF219 gene is a member of the Kruppel-like zinc finger gene family that are involved in many biological processes, such as cell growth, differentiation, embryogenesis and tumorigenesis, and ZNF219 is often depleted in the early stage of tumor progression." (PMID 29379079, 2018).
neurological diseases (1 paper, 2017). "The transcription factors CP2 and ZNF219 might represent a change in transcriptional regulation that is generally noted in neurological diseases." (PMID 28499347, 2017).
ZNF219 also shares sentences with these, for which no sentence is quoted: cancer (3 papers); Alzheimer disease (1); esophageal cancer (1); heart failure (1); infection (1); mild cognitive impairment (1); neurodegenerative disease (1).